IL1B (interleukin 1 beta)
Diseases named in the same sentence as IL1B in open-access papers (continued):
Sharing a sentence is not in itself a finding about the gene and the disease.
tumor (continued). "Subsequently, IL-1β stimulates the phosphatidylinositol-3-kinase (PI3K) pathway and phosphorylates the glycolytic enzyme glycerol-3-phosphate dehydrogenase (GPD3), thereby promoting the survival and proliferation of tumor cells." (PMID 40727443, 2025). "Research has clarified that M1 macrophages raised PIGR levels in BRCA cells employing IL-1β, suggesting that targeting M1 macrophages to increase PIGR may be a potential anti-tumor strategy." (PMID 41450825, 2025). "Furthermore, Amuc_C triggered IL-1β, TNF-α, and IFN-γ productions, significantly decreasing tumor growth, and prolonged overall survival." (PMID 41170411, 2025). "Combined with the spatial characterization of metastasis CAFs at the RNA and protein level, scRNA analyses indicate tumor‐dependent crosstalk between neutrophils and CAFs, mediated via SAA3 and IL1b‐related signaling pathways, which can be recapitulated in vitro." (PMID 39924882, 2025). "Cells with heightened receptor expression demonstrated an escalated production of cytokines and growth factors (e.g., interleukin-1 beta (IL-1β), hepatocyte growth factor (HGF), interleukin-8 (IL-8), VEGF), which were found to provide notable support to tumour progression." (PMID 41301715, 2025). "This dual modulation of inflammatory mediators—suppressing chronic inflammation (IL-1β, IFN-γ) while inducing acute immune activation (IL-6, TNF-α)—may reprogram the tumor microenvironment toward an immune-permissive state." (PMID 41401147, 2025). "While anti-IL-1β monotherapy and anti-PD-1 monotherapy also reduced tumor volume compared to control, it was not to the magnitude of the anti-PD-1 + anti-IL-1β combination." (PMID 39948655, 2025). "Among these, IL-1β, IL2, IL6 play critical roles in activating immune cells and amplifying proinflammation responses, while TNFα and IL27 can directly inhibit the growth of tumor cells." (PMID 40046011, 2025). "iCAFs are enriched at the liver site and the tumor-liver interface, ECM CAFs with C1QC+ and inflammatory IL1B+ macrophages at the tumor-liver border and in the tumor site, whereas myofibroblasts and immunosuppressive SPP1+ macrophages infiltrate the tumor core." (PMID 40393458, 2025). "A statistically significant difference was obtained in concentrations of IL-1β between the group of patients with coexisting non-neoplastic diseases and those without such diseases." (PMID 40429943, 2025). "Furthermore, the expression levels of TNF-α, IL-6, IL-1β, and NOS2 in tumor tissues were enhanced following CIRT treatment compared to the control group (p < 0.001)." (PMID 40917841, 2025). "In macrophages, NPs modulate cytokines such as Tumor Necrosis Factor (TNF)-α, nitric oxide (NO), interleukin-(IL)−10 (IL-10), and IL-1beta (IL-1β) secretion in both tumor and non-tumor cells." (PMID 40643749, 2025). "In addition, the DCs supplied with the supernatant from OVV-mNbTIM3-infected tumor cells produced much higher concentrations of IL-12, TNF-α, and IL-1β." (PMID 41291902, 2025). "After PD-1/Al@OV treatment, IL-1β and IL-6 levels were significantly reduced, while IFN-γ expression increased in tumor tissues, indicating that PD-1/Al@OV effectively enhanced the anti-tumor immune responses." (PMID 39955603, 2025). "Compared to the oe‐NC+M2pep‐Cs NPs/Plerixafor group, the mRNA levels of CD80, IL‐1β, and IL‐6 were significantly downregulated, and the mRNA levels of CD206 and IL‐10 were significantly upregulated in the tumor tissues of mice in the oe‐CXCR4+M2pep‐Cs NPs/Plerixafor group." (PMID 40536774, 2025). "NLRP3 activation may improve anti-tumour immunity in malignancies with low levels of IL-1β production, while NLRP3 inhibition may help stop tumour growth in tumours with high amounts of IL-1β." (PMID 40205269, 2025).
tumor (continued). "They found that interleukin-1β (IL-1β) and tumor necrosis factor-α (TNF-α) were primarily secreted by dendritic cells (DCs), and macrophages with a marked elevation in these cytokines in tumors colonized by ΔppGpp all through the phase of tumor suppression." (PMID 40519767, 2025). "Doenjang significantly reduced tumor formation and attenuated CAC progression by modulating inflammatory and apoptotic pathways and suppressed the expression of pro-inflammatory cytokines (TNF-α, IL-1β, and IL-6) by inhibiting the NF-κB pathway." (PMID 41154100, 2025). "GMDP signals through NOD2 on myeloid cells to release IL-1b and NLRP3 to induce cytotoxic granzyme B+CD8+ T cells in the tumor and enhances the efficacy of anti–CTLA-4, anti–PD-1, and anti–PD-L1 in different mouse tumor models." (PMID 39895632, 2025). "Collectively, non-B-FLCs drive inflammation and tumor progression by activating inflammasome by enhancing the expression of cleaved caspase-1 and the maturation of IL-1β and IL-18." (PMID 40806736, 2025). "Additionally, under oxidative stress induced by the tumor microenvironment, thioredoxin-interacting protein (TXNIP) interacts with the NLRP3 inflammasome, leading to IL-1β maturation and secretion, which correlates with postoperative RCC recurrence." (PMID 40718836, 2025). "For MICA/B and PD-L1 measurement, tumor cells were co-cultured with CM from M1 macrophages, with or without anti-IL-1β, anti-IL-6, and anti-TNF-α antibodies." (PMID 40369131, 2025). "CMTM4 regulates RTK function and further controls downstream signal activation, including NF-κB and Akt/mTOR pathways, which may induce tumor productions of various cytokines and chemokines in cancer cells, including CCL-1, IL-1β, G-CSF." (PMID 39948411, 2025). "In addition to this highly inflammatory phenotype, expression of other pro-inflammatory genes, such as IL1B, CXCL16, VEGFA and HBEGF, which can facilitate tumor progression and survival, were also observed." (PMID 41056512, 2025). "In turn, macrophages secrete IL-1β, which further upregulates LCN2 expression in tumor cells." (PMID 41436606, 2025). "Therefore, blocking AIM2 inflammasome or α1-AR reduces the production of bioactive IL-1β and reverses macrophage phenotype triggered by CAR-T therapy, thus enhancing an anti-tumor effect." (PMID 39857785, 2025). "In cell cultures and animal models, NF-κB is activated and upregulated during inflammation, thus boosting the expression of several pro-inflammatory cytokines such as IL-1β, IL-6, COX-2, and TNF-α and altering tumor inflammatory microenvironment to promote tumor cell survival." (PMID 39834867, 2025). "Studies indicate that cells do not produce large amounts of IL-1β at low grades, and expression increases with increasing tumor malignancy." (PMID 40429943, 2025). "Success markers include transient serum cytokine elevations (IL-6, IL-1β), improved tumor CD8+/Treg ratios, and conversion from non-inflamed to inflamed gene signatures in biopsies." (PMID 40227782, 2025). "Furthermore, downregulation of TPM2 activates ELANE of neutrophils to facilitate ERK1/2 activation, thus enhancing IL1β and IL8 secretion for chemoattraction of more neutrophils to tumor microenvironment." (PMID 40199876, 2025). "IL-1β, a pro-inflammatory cytokine primarily secreted by monocytes, macrophages, and dendritic cells, is known to activate NF-κB and MAPK signaling pathways within the tumor microenvironment." (PMID 41029721, 2025). "Furthermore, other factors including IL-1β, VEGF, CXCL1, and IL-6 can influence MDSC number in the tumor microenvironment, some of which are produced by PSCs." (PMID 40427186, 2025).
tumor (continued). "After tumour cells migrate to the endosteum, tumour cells stimulate the RANKL expression in osteoblasts through the production of PTHrP, prostaglandin E2, interleukin (IL)-6, IL-1β, enhancing osteoclastic bone resorption." (PMID 41027468, 2025). "Macrophages are the primary producers of numerous molecules that facilitate tumor angiogenesis, such as VEGFA, CXCL8 (chemokine (C-X-C motif) ligand 8), PlGF (placental growth factor), IL-1β (interleukin-1 beta), IL-6 (interleukin-6), TNF (tumor necrosis factor), MMPs, and cathepsins." (PMID 40940953, 2025). "In the PBMC cultures, IL-10, TGF-γ, IL-6, and IL-1β cytokine levels were not detectable, suggesting that matrix alone without tumor tissue is not sufficient to induce production of these cytokines from immune cells." (PMID 40425576, 2025). "Treatment of mice with an IL-1β-neutralising antibody had no clear effect on primary tumor growth, but effectively inhibited CTSC-increased levels of circulating IL-6 and CCL3, as well as lung metastasis in mice." (PMID 41019086, 2025). "They express the CCR2, CCR5, and CXCR2 chemokine receptors, which are then mobilized to the blood and tumor by chemokine ligands (CCL2, CCL5, CXCL1-8) and other inflammatory mediators like prostaglandin E2 (PGE2) generated by TME, VEGF, TGF-β, TNF-α, and IL-1β, IL-6, and IL-10." (PMID 40727443, 2025). "This immune reprogramming can be mediated through sustained exposure to tumor-derived cytokines such as IL6 (interleukin-6), TNFα (tumor necrosis factor-alpha), IL1β (interleukin-1 beta), TGFB (transforming growth factor beta), chemokines, growth factors, and extracellular vesicles." (PMID 41514627, 2025). "In both WT and Il1b–/– mice, persistent B cell activation in response to HDM may contribute to the creation of a pro-tumor microenvironment by promoting tissue remodeling, immune suppression, and chronic inflammation." (PMID 41445736, 2025). "IL‐1β also promotes MDSC differentiation by triggering the secretion of chemokines like CXCL1 and CXCL2, which attract MDSCs to the tumor site, thus reinforcing the tumor‐promoting functions within the TME." (PMID 39558859, 2025). "The expression profiles of IL1β, IL10, IL18, TNF-α, TLR4, GATA3, and CD68 in HHV-infected PCa FFPE biopsies indicated an inflammatory environment conducive to immune alteration and potential tumour progression." (PMID 40430084, 2025). "This chronic inflammatory state promotes the release of cytokines (e.g., IL-1β, IL-6, IL-10, IL-18, TNF-α) and growth factors that facilitate tumor cell proliferation, invasion, and angiogenesis, while simultaneously impairing effective immune surveillance against malignant cells." (PMID 41114747, 2025). "IHC staining was performed for eight cytokine proteins—TNF-α, IFN-γ, TGF-β1, IL-1α, IL-1β, IL-2, IL-6, and IL-12—in paired PeCa tumour samples and corresponding negative-margin tissue." (PMID 41465261, 2025). "Additionally, the Ganoderma atrum polysaccharide (PSG-1) activated macrophages and increased the production of TNF-α, IL-1β, and NO via p38 MAPK in the murine CT26 tumor model." (PMID 41019059, 2025). "The combination of anti-IL-1β and anti-PD-1 antibodies does not slow primary tumor growth but prolongs overall survival and reduces lung metastasis rates in a PDAC orthotopic murine model with lung metastasis tropism." (PMID 39948655, 2025). "In the same network, IL-1β interacts with ADRB2; hence, recent findings highlight mechanisms through which the hypoxic tumor microenvironment may contribute to BC progression and suggest additional therapeutic targets." (PMID 41150737, 2025). "CAAs differ from “normal” adipocytes as they display fibroblast-like morphology, usually contain several dispersed small lipid droplets, and produce increased amounts of inflammatory cytokines IL-1β, IL-6, IL-8, TNF, chemokines (CCL2, CCL5), and leptin, which altogether facilitate tumor progression." (PMID 40940764, 2025).
tumor (continued). "Additionally, IL-18, IL-1β, and LDH were released to the extracellular environment, thereby activating anti-tumor immune responses." (PMID 39743555, 2025). "IL-1B and TNF expression were higher in the tumor group compared to the normal group." (PMID 39744500, 2025). "However, studies suggest that reduced IL-10 expression permits increased angiogenesis and heightened activity of VEGF, IL-1β, TNF-α, IL-6, and NF-κB, ultimately enhancing tumor growth." (PMID 40100373, 2025). "They prevent tumor growth through the secretion of pro-inflammatory cytokines known to inhibit tumor progression, including tumor necrosis factor-alpha (TNF-α), interleukin-1β (IL-1β), IL-6, IL-8, IL-12, and IL-23." (PMID 39857798, 2025). "Again, it should be noted that CAFs in the KPC-3403 tumor following the anti-IL-1β + anti-PD-1 combo treatment are not assessable due to the small tumor size." (PMID 39948655, 2025). "Stimulation of IL-1β secretion by GF + PTX (p < 0.0001) and GFAP + PTX (p < 0.0001) between 12 h and 24 h of incubation suggests the consequences of the prolonged exposure of tumor cells to the chemotherapeutic agent." (PMID 39940603, 2025). "In addition, the transcription levels of the markers of M1 macrophages, TNFα, IL12, and IL1b, were significantly upregulated after co‐culturing with PBRM1 knockdown tumor cell culture medium." (PMID 39656940, 2025). "Since tumor cells are not involved in the response to pathogens or other perturbations of the general homeostasis, their synthesis of IL-1β is a less obvious and expected event than for immune cells." (PMID 39858071, 2025). "Syngeneic graft experiments with MC38 cells overexpressing YY2 showed that BUB1B knockdown abolished the YY2 tumor suppressive effect, as well as its positive impact on chromosome missegregation, caspase‐1/GSDMD activation, IL‐1β, and cell death rate in syngeneic graft lesions." (PMID 39903759, 2025). "For instance, exosomes released from HepG2 cells treated with ezetimibe do not induce inflammasome activation or IL-1β secretion, suggesting that exosomal cargo composition is sensitive to the metabolic state of the tumor cells." (PMID 40141358, 2025). "It should be noted that the analysis was not feasible for the KPC-3403 tumor treated with the combination of anti-PD-1 and anti-IL-1β due to the small tumor size and thus low cell count in the snRNA-seq sample." (PMID 39948655, 2025). "Inflammatory mediators—such as TNF‐α, IL‐1β, iNOS, and COX2—act as molecular accelerants of tumor initiation and progression by fostering genomic instability, promoting cellular proliferation, and suppressing tumor immune surveillance." (PMID 41200213, 2025). "Previous studies suggested that IκBζ target genes, such as IL1A, IL1B, or IL6, promote tumor cell proliferation, although it is unclear whether these cytokines are predominantly produced by the tumor cells or the surrounding TME19–21." (PMID 40562773, 2025). "Macrophages are a likely source of TNF-α within the tumour microenvironment, as supported by the upregulation of genes involved in TNF-α and IL-1β production in macrophages that had engulfed native bacteria in patient colorectal and oral squamous cell carcinoma samples." (PMID 39272829, 2024). "However, in addition to SPP1+ and C1QC+ TAM populations, tumour-infiltrating monocytes have been identified and described as other cancer-specific moTAM subsets including TREM2+ TAM and IL-1β+ TAM." (PMID 39430099, 2024). "In addition, the serum and tumor homogenate concentrations of proinflammatory cytokines, including IFN‐γ, TNF‐α, IL‐6 and IL‐1β, increased significantly in the B16F10 cell–rechallenged mice of the HM‐NPs group." (PMID 38353384, 2024). "In our study we saw a higher IL1b transcript level in both age groups (≤ 60 and > 60) and locations (larynx and oral cavity) in men but not women, in all histologic grade stages (G1-G3) and T3-T4 and N0, N2 TNM tumor stages." (PMID 38175424, 2024).
tumor (continued). "The activation of nuclear factor-κB (NF-κB) and associated signaling pathways and cytokines, such as TNFα, IL-6, and IL-1β, plays a key role in the development of CAC, which leads to imbalances in cell proliferation and differentiation and tumor transformation initiation." (PMID 39063041, 2024). "VGX-1027, a compound that targets macrophages to reduce the production of TNF-α and IL-1β, was also used to verify whether SPP1 + Mac-derived TNF-α and IL-1β act on tumor cells." (PMID 39726047, 2024). "Another study showed that HMGB1, synergistically with ATP, could induce DCs to release interleukin‐1β (IL-1β), and HMGB1-specific antibodies can block the ability of IL-1β production in DCs after exposure to dying tumor cells." (PMID 38384466, 2024). "Its activation leads to increased secretion of pro-inflammatory cytokines such as IL-6, IL-1β, and TNF-α, which may promote inflammation and support a pro-tumor environment." (PMID 39273213, 2024). "IL1B and IL1R1 expression was significantly low in the case of tumours/cells with relatively long telomeres and notably consistent across clinical tissue, organoids, xenografts and cells, in contrast to the other cytokines which showed model-specific variation." (PMID 39728924, 2024). "By increasing IL-1β release through NLRP3 inflammasome accumulation and by macrophage self-recruitment through the CCL20 signaling pathway, the findings demonstrated that inhibiting tumor macrophage autophagy enhanced the advancement of HCC." (PMID 39315094, 2024). "IL-1β and IL1RN can promote tumor angiogenesis and the recruitment of immune suppressor cells." (PMID 39684426, 2024). "The infection and subsequent lysis of tumor cells by oncolytic viruses lead to the release of proinflammatory molecule cascades into the TME, including type 1 interferons, DAMPs, PAMPs, IL-18, IL-1β, and also tumor antigens, generating robust antiviral and antitumor immune responses." (PMID 39066359, 2024). "In this study, we report that mEHT monotherapy stimulated interleukin‐1 beta (IL‐1β) and interleukin‐6 (IL‐6) expression, and consequently cyclooxygenase 2 (COX‐2), which may favor a cancer‐promoting tumor microenvironment." (PMID 38217262, 2024). "While much evidence points to a negative role of IL-1β on tumor initiation and progression, these studies largely rely on chronic inflammation models." (PMID 38391959, 2024). "The IL-1β/NFκB and IL-6/STAT3 signaling networks have well-established tumor-promoting functions." (PMID 39260693, 2024). "The observed link between the IL-1β/IL-1RA axis and AKT signaling may indicate possible autophagy activation processes besides the known tumor-promoting effects of AKT." (PMID 38397123, 2024). "In contrast, TAM (tumor‐associated macrophage) C16 was enriched in lung tumors and highly expressed PDE4B but not IL1B, MDM2, or PELI1." (PMID 38010945, 2024). "Furthermore, the decrease in IL37 expression accompanied by MCC950 treatment also resulted in reduced IL1β expression, further verifying that elevated IL37 serves as a self‐protective mechanism for tumour cells against inflammation." (PMID 39500733, 2024). "The DMPtNPS@cGAMP + RT group exhibited a significant increase in anti‐tumor cytokines, namely IFN‐γ, IFN‐α, IFN‐β, TNF‐α, and IL‐2, and a more pronounced decrease in pro‐tumor cytokines, including IL‐1β, IL‐10, IL‐4, and TGF‐β, as measured by ELISA kits, in comparison to the other treatment groups." (PMID 38063844, 2024). "Moreover, CXCL5 and IL-1β secreted by tumor cells correlated significantly to PMN-MDSCs accumulation, and antagonism against IL-1β or CXCR2 retarded tumor growth." (PMID 38649887, 2024). "LMP1-mediated induction of the NF-κB pathway may result in the activation of IL-1α and IL-1β promotors, and the ample production of IL-1α and IL-1β may facilitate lymphocyte infiltration of an NPC tumour." (PMID 38675906, 2024).